INS (insulin)
Diseases named in the same sentence as INS in open-access papers (continued):
Sharing a sentence is not in itself a finding about the gene and the disease.
Hyperglycemia (continued). "Therefore, the machinery that controls insulin secretion in response to glucose is impaired in tau KI mice, probably contributing to hyperglycemia observed in these mice." (PMID 35250480, 2022). "According to present evidence, one of the damage mechanisms is liver injury, which may impair insulin signaling, leading to a failure to suppress glucose production and ultimately hyperglycemia." (PMID 35318741, 2022). "Furthermore, peptides have been reported to play other significant roles in the control of hyperglycemia such as encouraging insulin secretion, promoting glucose absorption in peripheral tissue or decreasing its absorption in the gut." (PMID 36161374, 2022). "Insulin use may reflect poor glycemic control, and it was reported that hyperglycemia reduces vascular endothelial function and that DM reduces the use of NO." (PMID 36078984, 2022). "Taken together, patients with severe proteinuria at dialysis initiation might have been exposed to hyperglycemia refractory to oral antidiabetic agents before the start of insulin therapy, resulting in the progression of microangiopathy." (PMID 35213636, 2022). "However, it promotes hyperglycemia in roughly 15% of human patients, presumably by promoting systemic and hepatic insulin resistance and diminishing pancreatic response to glucose." (PMID 35986566, 2022). "This implies that Glycyrrhiza extract can help with insulin sensitivity and hyperglycemia." (PMID 35268815, 2022). "As a consequence of the destruction to the pancreatic beta cells, insulin shortage occurs, leading to hyperglycemia, which could be either T1DM or T2DM." (PMID 35268815, 2022). "In such cases, hyperglycemia results from defects in insulin secretion and/or insulin action." (PMID 36743910, 2022). "However, the infant developed hyperglycemia related to the rapamycin dose, which was effectively controlled by adjusting the dose and applying insulin." (PMID 35865311, 2022). "Increased blood sugar (hyperglycemia) and impaired glucose metabolism occur either as a result of decreased insulin secretion or due to decreased sensitivity of the body cells to the action of this hormone (insulin)." (PMID 35890983, 2022). "Thus, DPP-IV inhibition increased incretin hormone levels, leading to increased insulin secretion and reducing postprandial and fasting hyperglycemia." (PMID 36496713, 2022). "While we were unable to assess the effects of reduced insulin gene dose in males using this model, as Ptf1aCreER;KrasLSL-G12D;Ins1+/-;Ins2-/- males developed hyperglycemia, these studies were the first to directly demonstrate that endogenous hyperinsulinemia contributes to development of any cancer." (PMID 35189981, 2022). "Thus, it can be concluded that the key defect leading to the deterioration of hyperglycemia after diabetic pregnancy is impaired insulin secretion due to beta cell failure." (PMID 36499008, 2022). "Chronic inflammation, hyperglycemia, hyperinsulinemia, and abnormalities in insulin/insulin-like growth factor 1 (IGF-1) pathways are some of the proposed molecular mechanisms by which DM and PC are closely related, with emerging evidence showing a positive association between DM and the risk of PC." (PMID 35898377, 2022). "In response to elevated glucose levels, MVS could quickly release insulin and provide a more efficient reduction of hyperglycemia than its control counterparts." (PMID 35903090, 2022). "Taken together, these results demonstrate that SELENOF KO led to hyperglycemia and serum insulin reduction in young mice and serum insulin reduction might have been one of the causes of hyperglycemia." (PMID 36358477, 2022). "Whey protein is an excellent source of branched-chain amino acids (BCAAs) and it has been shown that after its digestion, a rapid increase in amino acids, particularly BCAAs leads to insulin release, which may improve postprandial hyperglycemia." (PMID 35215472, 2022).
Hyperglycemia (continued). "Groups treated with isoflurane and the combination of iron dextran + isoflurane show higher blood glucose levels, respectively, and hyperglycemia as a consequence of prevented exocytosis of insulin from pancreatic beta cells resulting from the harmful effects of isoflurane." (PMID 35453393, 2022). "Moreover, emodin ameliorated hyperglycemia and dyslipidemia owing to the alleviation of insulin resistance and improvement of insulin sensitivity in a concentration- and time-dependent manner." (PMID 36386943, 2022). "Besides the regulation of lipid metabolism, dehydroepiandrosterone was also proved to decrease hyperglycemia and increase insulin sensitivity." (PMID 36061360, 2022). "The results obtained in that study indicate that treatment with this mixture is more effective than the standard drugs (insulin and metformin) in the amelioration of hyperglycemia, hyperlipidemia, and histopathological changes of the pancreas, kidney, and liver tissue." (PMID 35899227, 2022). "Interestingly, this effect was believed to be modulated by hyperglycemia since treatment with insulin and control of blood glucose levels reversed the expression of kininogen." (PMID 35610262, 2022). "Indeed, previous studies in humans reported that the interaction between exercise-induced AMPK phosphorylation and the subsequent insulin-stimulated activation of GLUT4 alleviates 24-h hyperglycemia." (PMID 35928886, 2022). "The effects of different insulin subtypes and dosing strategies on hyperglycemia." (PMID 35634376, 2022). "Even though hyperglycemia can be managed with insulin or antihyperglycemic drugs, diabetic retinopathy remains the leading cause of blindness since oxidative stress may play a role in the development of retinopathy." (PMID 35637465, 2022). "In addition, hyperglycemia promotes the suppression of cytokine signaling action, thereby impairing insulin release and signaling cascades." (PMID 35937787, 2022). "Many authors have proposed that postprandial hyperglycemia is controlled more effectively when the insulin dose is calculated for both the carbohydrates and fat-protein nutrients yet calculating the fat protein unit has not become standard practice since today although suggested a while ago." (PMID 35330014, 2022). "Intensive insulin therapy was started for hyperglycemia, which required more than 40 units/day." (PMID 35637924, 2022). "In addition, steroids can induce hyperglycaemia, insulin requirements, and superimposed bacterial infections or even sepsis during COVID-19 hospitalization, complicating recovery." (PMID 35740079, 2022). "In addition, in the presence of hyperglycemia, it is recommended that rapid-acting insulin analogues are always administered in advance of the meal." (PMID 36510287, 2022). "IL-18 may attenuate lipid metabolism, postprandial hyperglycemia, and modulate insulin signalling and by triggering endothelial inflammation, promote the formation of atherosclerotic plaques." (PMID 35160217, 2022). "GLP-1 controls meal-related hyperglycemia via insulin augmentation and inhibits food intake." (PMID 35208221, 2022). "Using the model system Drosophila melanogaster, we demonstrate that central Hmgcr activity, via the mevalonate pathway, regulates insulin signaling, leading to increased lipid storage, hyperglycemia, and hyperphagia and that this regulation is dependent on carbohydrate consumption." (PMID 35326421, 2022). "Therefore, it is important to consider tight insulin glycemic control to be considered in ACS patients with significant hyperglycemia (>180 mg/dL)." (PMID 35629267, 2022). "Sulfonylurea (SU) or a high dose of insulin is commonly used for hyperglycemia at admission." (PMID 35050147, 2021). "During hyperglycaemia, the stimulus to upregulate insulin secretion therefore promotes hypoxia, and hypoxic effects on mitochondria have been found to increase production of mitochondrial reactive oxygen species (ROS) through heightened oxidative phosphorylation." (PMID 34260650, 2021).
Hyperglycemia (continued). "Thus, T1D treatment consists in insulin replacement by means of subcutaneous administration of insulin analogs in order to avoid the long-term complications due to hyperglycemia." (PMID 34064325, 2021). "In our study, CGM reliably identified hyperglycaemia and could potentially help guide insulin treatment during exacerbations." (PMID 33855211, 2021). "Another fucoidan from U. pinnatifida reduced blood glucose levels and improved insulin sensitivity in mice and decreased basal lipolysis in 3T3-L1 adipocytes which may reduce hyperglycaemia by glucose uptake." (PMID 33440853, 2021). "Therefore, i-Beta cells, similar to normal human beta cells or other stem-cell-derived Beta cells, were capable of secreting insulin and rapidly ameliorating hyperglycemia in a diabetic mouse." (PMID 34055806, 2021). "It is interesting to observe that in two models of increased metabolic demand (congenital leptin deficiency and pregnancy), Igf2βKO females exhibited hyperglycaemia, while in the third (HFD feeding) Igf2βKO females were normoglycaemic and more insulin sensitive than their controls." (PMID 33833312, 2021). "Also insulin mediated glucose reductions did partially negate the protection rendered by hyperglycemia on AA." (PMID 34820431, 2021). "The liver is preferentially used to dispose over 50% of the ingested glucose and restrict the acute increases of glucose and insulin in the bloodstream after meals, thus protecting the circulation and tissues from the adverse effects of marked hyperglycemia and hyperinsulinemia." (PMID 33419065, 2021). "Independent manipulation of BG and insulin levels in an animal model of hyperglycaemia (burn injured parenterally fed rabbit), demonstrated survival to be better in the normoglycaemic groups (89% verses those with hyperglycaemia 53–64%)." (PMID 34368024, 2021). "Therefore, insulin therapy in people with liver cirrhosis requires close monitoring of blood glucose levels to avoid the risks of hypoglycemia or hyperglycemia." (PMID 34118892, 2021). "Despite the increased levels of insulin, burned patients have persistent hyperglycemia." (PMID 34068151, 2021). "Furthermore, they showed that monoclonal antibody neutralizing circulating MG53 improves hyperglycemia and enhances insulin sensitivity in db/db mice." (PMID 33566837, 2021). "We found that women affected by both (elevated fasting and post‐load hyperglycaemia) showed adverse metabolic profiles including a higher degree of insulin resistance at beginning of pregnancy as compared to NGT women or to those with isolated abnormalities of glucose metabolism." (PMID 34120352, 2021). "The arising hyperglycemia can lead to insulin overproduction (hyperinsulinemia) in the fetus." (PMID 34946940, 2021). "Insulin intensification targets postprandial hyperglycemia and can be accomplished either by adding one (basal-plus) or more (basal-bolus) prandial insulin injections, or by adding a GLP-1 receptor agonist (GLP-1 RA) if the patient is not already under such therapy." (PMID 34063071, 2021). "The physiological effect of insulin counteracts the deteriorating effect of hyperglycemia on cardiovascular outcomes which could explain why it failed the mediator tests." (PMID 34583686, 2021). "However, uncontrolled hyperglycaemia during pregnancy is partially due to decreased insulin sensitivity by almost 60%." (PMID 34513891, 2021). "In addition, when injected in a transgenic mouse model mimicking T2DM in humans, the mAb was able to reduce hyperglycemia, fibril formation in the islets, and decreased inflammation, while insulin-production remained largely normal." (PMID 34835247, 2021). "When insulin is absent or its function is impaired, cells are unable to absorb glucose, which remains in the bloodstream causing hyperglycemia." (PMID 34366888, 2021).
Hyperglycemia (continued). "This fundamental role of hormone–receptor interactions in the context of body energy repletion and depletion explains why concentrations of insulin and leptin rise in obese persons and animals and why insulin becomes less effective in suppressing hyperglycemia and hyperlipidemia." (PMID 34836068, 2021). "Our hypotheses were that (i) hyperglycemia accelerates liver pathology compared to effects of a high-fat diet alone and that (ii) insulin therapy improves liver pathology by preventing or reversing hepatic steatosis, inflammation and fibrosis." (PMID 33596938, 2021). "Defective respiration and thus decreased fat consumption was attributed as a major factor driving steatosis, while mitochondrial ROS-mediated c-Jun-N terminal kinase (JNK) activation was responsible for the disruption of insulin signaling that promotes hyperglycemia." (PMID 33276146, 2021). "Furthermore, postoperative inflammation triggers the development and sustenance of hyperglycemia by inducing insulin resistance and accelerating gluconeogenesis." (PMID 32772168, 2021). "Preclinical studies indicate that oleuropein improves glucose transport, increases insulin sensitivity, and facilitates insulin secretion by pancreatic β-cells, thereby supporting the hypothesis of the possible benefits of the control of hyperglycemia." (PMID 35056936, 2021). "In some women, pancreatic beta cells are unable to sustain this increased production of insulin, and so blood sugar levels are not kept within the normal range, thus causing the hyperglycemia that characterizes GDM." (PMID 34681954, 2021). "First, corticosteroids may contribute to hyperglycemia through decreasing peripheral sensitivity to insulin, increasing liver gluconeogenesis, increasing lipolysis, and reducing muscle and adipose tissue glucose uptake." (PMID 33808901, 2021). "One of the suggested explanations is that hyperhomocysteinemia increases vascular oxidative stress, which could relate to insulin resistance and impaired insulin secretion during hyperglycemia." (PMID 33498674, 2021). "Increased liver fat and high plasma triacylglycerol (TAG) concentrations expose pancreatic β-cells to excess circulating fatty acids and locally deposited tissue TAG, with the subsequent lipotoxicity inhibiting insulin secretion and promoting postprandial hyperglycaemia." (PMID 34094511, 2021). "Duration of hyperglycemia after injection of 50% dextrose at all three different concentrations was significantly greater for healthy rats than diabetic rats, suggesting that insulin infusion by APS was superior in reducing BGL as compared to natural insulin released from pancreatic β-cells." (PMID 34270619, 2021). "In particular, type 2 diabetes (T2D) is currently one of the most frequently reported causes of endothelial and vascular dysfunction resulting from increased hyperglycemia and disruption of insulin signaling, ultimately leading to the development of cardiovascular diseases." (PMID 34207844, 2021). "These pro-inflammatory markers could inhibit insulin signalling pathways, leading to insulin resistance, dysfunction of β-cells, hyperglycaemia, and the occurrence of T2DM." (PMID 34955840, 2021). "It was also associated with a significant increase in the risk of hyperglycemia and insulin requirement and did not affect significantly the incidence of HAP-VAP and/or ICU-BSI." (PMID 34347836, 2021). "Continuous exposure to hyperglycemia and elevated concentrations of circulating insulin might stimulate cancer growth and progression, leading to poorer prognosis." (PMID 34830886, 2021). "In Pedersen's hypothesis, maternal hyperglycemia passing through the placental barrier stimulates the fetus to secrete more insulin which promotes fat and protein accumulation, leading to excessive fetal growth." (PMID 34301212, 2021).
Hyperglycemia (continued). "Limonium axillare may be an antidiabetic remedy that can reduce hyperglycaemia and restore serum insulin levels by increasing the expression of the glucose transporters GLUT2 and GLUT4." (PMID 34827690, 2021). "There is no clear evidence available to distinguish between which of the two treatment strategies, being the achievement of a physiological state of euglycemia or the administrating insulin, improves survival in critically ill “cardiovascular” patients subject to stress hyperglycemia." (PMID 33463901, 2021). "Furthermore, increased corticosteroids inhibit insulin release and decrease insulin tissue uptake leading to initial hyperglycaemia." (PMID 35784407, 2021). "We showed that transplantation of DHA/EPA altered gut microbiota to recipient mice successfully counteracted hyperglycemia and enhanced insulin production, together with the enriched abundance of Coriobacteriaceae (OTU19898), Barnesiella (OTU136), and Clostridium XlVa (OTU57)." (PMID 34507608, 2021). "XPA binding protein 2 (XAB2) exerts as a regulator in hyperglycemia with chronic insulin." (PMID 34084770, 2021). "In addition, increased fasting blood glucose and insulin levels were observed in KO chimera compared to WT chimera, indicating the development of hyperglycemia and hyperinsulinemia in the KO chimera." (PMID 34091599, 2021). "The slower achievement of maximal postprandial plasma insulin concentration and increased peripheral insulin resistance, together impede postprandial glucose uptake, facilitating the prolonged duration of postprandial hyperglycemia in late pregnancy." (PMID 33512267, 2021). "One patient was excluded after visit 1 as insulin was started for significant hyperglycaemia." (PMID 33855211, 2021). "After food ingestion and the subsequent increase in insulin levels, the suppression of glucose production is slower in a diabetic patient, promoting an evident postprandial hyperglycemia due to the excess of glucose produced in addition to that from the exogenous source." (PMID 35002743, 2021). "Generally, subcutaneous insulin is used to manage hyperglycaemia in acute stroke." (PMID 34640636, 2021). "Hyperglycemia in type 1 diabetes (T1D), resulting from the autoimmune destruction of pancreatic β-cells, is controlled by direct insulin administration, but this therapy cannot accomplish exact physiological control of blood glucose concentrations and complications continue to progress." (PMID 33803588, 2021). "Intranasal (IN) administration of insulin helps in controlling hyperglycemia." (PMID 34540446, 2021). "Ultimately, our goal is to study whether insulin initiation upon admission in CF patients with hyperglycaemia can improve recovery from the exacerbation." (PMID 33855211, 2021). "Taken together, this vicious stress cycle could lead to beta cell exhaustion resulting in beta cell death, decreased insulin secretion, increased hyperglycemia, and phenotypic manifestation as Type 2 diabetes." (PMID 33868167, 2021). "The experimental loss of the hepatic GHR/JAK2/STAT5 signal cascade dramatically reduces circulating IGF1 levels, leading to a rise in circulating GH levels and thereby reducing systemic insulin sensitivity, leading to hyperinsulinemia, hyperglycemia, and WAT lipolysis." (PMID 34685512, 2021). "The focus of current therapies for T2D are treating hyperglycaemia via enhanced insulin production, which may be achieved via drugs such as sulphonylureas, or alternatively enhancing insulin sensitivity via medications such as metformin." (PMID 34940547, 2021). "Insulin, given in intensive care units (ICUs) in response to donor hyperglycaemia, may modulate the inflammatory, metabolic and thrombotic responses to brain death as well as controlling glucose levels." (PMID 33665687, 2021).